DDX19B (DEAD-box helicase 19B)
Description:
ATP-dependent RNA helicase involved in mRNA export from the nucleus. Rather than unwinding RNA duplexes, DDX19B functions as a remodeler of ribonucleoprotein particles, whereby proteins bound to nuclear mRNA are dissociated and replaced by cytoplasmic mRNA binding proteins.
Synonyms: DBP5; DDX19; RNAh
Tractability: Small molecule: a structure with a bound ligand is known; it has a high-quality binding pocket. PROTAC: ubiquitination databases record sites on it; its protein half-life has been measured.
Gene: Protein-coding gene on chromosome 16 (70,289,663 to 70,335,305, forward strand). Ensembl gene ENSG00000157349.
Subcellular location: Cytoplasm; Nucleus, nucleoplasm
Subcellular location (Human Protein Atlas): Nucleoplasm
Gene Ontology:
Molecular function: ATP hydrolysis activity; protein binding; helicase activity; RNA binding; ATP binding; nucleic acid binding; RNA helicase activity
Biological process: mRNA export from nucleus
Cellular component: extracellular exosome; membrane; cytoplasm; cytoplasmic stress granule; nuclear pore; nucleoplasm
Genetic constraint (gnomAD): Loss-of-function variants: 23 observed, 51.29 expected, observed/expected ratio (o/e) 0.45, 90% interval 0.32 to 0.63. The upper end of that interval is the gene's LOEUF score, 0.63, which puts it in group 2 of 6, group 1 being the genes least tolerant of losing a copy. Missense variants: 379 observed, 589.81 expected, observed/expected ratio (o/e) 0.64, 90% interval 0.59 to 0.7. Synonymous variants: 183 observed, 212.34 expected, observed/expected ratio (o/e) 0.86, 90% interval 0.76 to 0.97.
Homologues: Orthologues: dog DDX19B (97% identical), mouse Ddx19b (97% identical), guinea pig DDX19B (95% identical), pig DDX19B (95% identical), rabbit DDX19B (95% identical), rat Ddx19b (94% identical), zebrafish ddx19b (86% identical), tropical clawed frog ddx19b (86% identical), zebrafish ddx19a (79% identical). Paralogues in human: DDX19A (96% identical), DDX25 (65% identical), EIF4A1 (33% identical), EIF4A2 (32% identical), EIF4A3 (31% identical), DDX6 (28% identical), DDX20 (27% identical), DDX4 (27% identical), DDX1 (27% identical), DDX39B (27% identical), DDX3X (27% identical), DDX42 (27% identical), and 26 more.
Diseases named in the same sentence as DDX19B in open-access papers:
DDX19B is named in the same sentence as 6 diseases in open-access papers, as found by Europe PMC text mining. Sharing a sentence is not in itself a finding about the gene and the disease. The quoted sentences say what the papers report.
thyroid cancer (3 papers, 2020 to 2022). "This method was validated by stably transfecting two standard human thyroid cancer cell lines (BCPAP and 8505C) with four distinct genes (DDX19B, NEMP1, PANK2, UBALD1) and profiling their transcriptome before and after the transfection." (PMID 33302383, 2020). "Nonetheless, we validated the relationship between the GCH score and the transcriptomic consequences of manipulating the gene expression by stably transfecting DDX19B, NEMP1, PANK2, and UBALD1 on the papillary (BCPAP) and anaplastic (850C) human thyroid cancer cell lines." (PMID 34209090, 2021).
viral infection (1 paper, 2016). "This apparent contradiction with the fact that upon depletion, both DDX19A and DDX19B appear to play a role in viral infection, is likely due to a high expression level of the recombinant DDX19B protein." (PMID 27653209, 2016).
cancer (3 papers, 2019 to 2021). A tumor composed of atypical neoplastic, often pleomorphic cells that invade other tissues. "Thus, we speculated ZC3H13, IGF2BP3, and DDX19B might participate in the occurrence and development of HCC through regulating their correlated AS events and inducing dysregulation of above cancer-related pathways." (PMID 34312475, 2021). "Although DDX19B and PANK2 (but not NEMP1 and UBALD1) were synergistically expressed with SPINT2 in PTC, there are no reports relating these genes with SPINT2 in any form of cancer." (PMID 32887258, 2020).
DDX19B also shares sentences with these, for which no sentence is quoted: Cognitive impairment (1 paper); depression (1); infection (1).